RNF113A (ring finger protein 113A)
Description:
Required for pre-mRNA splicing as component of the spliceosome. As a component of the minor spliceosome, involved in the splicing of U12-type introns in pre-mRNAs (Probable). E3 ubiquitin-protein ligase that catalyzes the transfer of ubiquitin onto target proteins. Catalyzes polyubiquitination of SNRNP200/BRR2 with non-canonical 'Lys-63'-linked polyubiquitin chains. Plays a role in DNA repair via its role in the synthesis of 'Lys-63'-linked polyubiquitin chains that recruit ALKBH3 and the ASCC complex to sites of DNA damage by alkylating agents. Ubiquitinates CXCR4, leading to its degradation, and thereby contributes to the termination of CXCR4 signaling.
Synonyms: RNF113; ZNF183; Cwc24; TTD5
Tractability: Small molecule: a structure with a bound ligand is known. PROTAC: ubiquitination databases record sites on it; its protein half-life has been measured.
Gene: Protein-coding gene on chromosome X (119,870,475 to 119,871,733, reverse strand). Ensembl gene ENSG00000125352.
Subcellular location: Nucleus; Nucleus speckle
Subcellular location (Human Protein Atlas): Nucleoplasm
Pathways (Reactome):
Metabolism of RNA: mRNA Splicing - Major Pathway
Gene Ontology:
Molecular function: protein binding; ubiquitin protein ligase activity; ubiquitin-protein transferase activity; metal ion binding
Biological process: mRNA splicing, via spliceosome; negative regulation of chemokine-mediated signaling pathway; protein ubiquitination
Cellular component: nuclear speck; nucleoplasm; nucleus; spliceosomal complex; U12-type catalytic step 2 spliceosome; U2-type precatalytic spliceosome; U2-type spliceosomal complex
Homologues: Orthologues: chimpanzee RNF113A (99% identical), macaque RNF113A (98% identical), dog RNF113A (95% identical), rabbit RNF113A (92% identical), mouse Rnf113a2 (89% identical), guinea pig RNF113A (88% identical), rat Rnf113a2 (88% identical), rat Rnf113a1 (88% identical), mouse Rnf113a1 (88% identical), tropical clawed frog rnf113a (66% identical), zebrafish rnf113a (66% identical), Drosophila melanogaster mdlc (56% identical), and 1 more. Paralogues in human: RNF113B (68% identical).
Diseases named in the same sentence as RNF113A in open-access papers:
RNF113A is named in the same sentence as 13 diseases in open-access papers, as found by Europe PMC text mining. Sharing a sentence is not in itself a finding about the gene and the disease. The quoted sentences say what the papers report.
small cell lung carcinoma (4 papers, 2022 to 2024). Small cell lung cancer (SCLC) is a highly aggressive malignant neoplasm, accounting for 10-15% of lung cancer cases, characterized byrapid growth, and early metastasis. "The latest research suggested that SMYD3-mediated methylation of RNF113A impedes small cell lung cancer sensitivity to DNA alkylation damage." (PMID 37237385, 2023). "The methyltransferases SMYD3 promotes RNF113A K20me3 methylation modification while impairing the interaction with phosphatase PP4, which downregulates its phosphorylation level, promotes and maintains RNF113A E3 ligase activity, and inhibits chemo‐sensitivity in small cell lung cancer." (PMID 38783893, 2024). "RNF113A methylation by SMYD3 improves alkylation damage response and impairs small cell lung cancer sensitivity to alkylation-based chemotherapy." (PMID 35819319, 2022). "In small cell lung cancer, a Ras-independent cancer, SMYD3 methylates another nonhistone substrate, the ubiquitin ligase ring finger protein 113A (RNF113A), promoting resistance to alkylating chemotherapeutics." (PMID 37976356, 2023).
lung carcinoma (3 papers, 2020 to 2022). "Here we show that RNF113A, whose loss-of-function causes the X-linked trichothiodystrophy, is overexpressed in lung cancer and protects from Cisplatin-dependent cell death." (PMID 32152280, 2020). "On the other hand, RNF113A deficiency enhanced cell death in Cisplatin-treated lung cancer A549 and BZR-T33 cells." (PMID 32152280, 2020). "RNF113A expression is upregulated in lung cancer, leading to resistance to DNA damage induced by cisplatin." (PMID 34742351, 2021). "RNF113A promotes cell survival in Cisplatin-treated lung cancer-derived cells as a subunit of the spliceosome." (PMID 32152280, 2020). "Despite the fact that RNF113A was found in the nucleus of lung cancer cells, Cisplatin enriched the cytoplasmic pool of RNF113A." (PMID 32152280, 2020). "Whether RNF113A-mediated dual downstream effector models exist in lung cancer cells is still unknown." (PMID 34742351, 2021). "Therefore, the spliceosome is a major actor of cell survival in lung cancer and also define RNF113A as a promising anti-cancer target to fight the acquired resistance to BCL-2 inhibitors." (PMID 32152280, 2020). "Therefore, targeting RNF113A or SF3B2 is a strategy to circumvent the acquired resistance of lung cancer cells to Cisplatin." (PMID 32152280, 2020). "Therefore, RNF113A expression is induced by some DNA-damaging signals and is increased in lung cancer." (PMID 32152280, 2020). "Therefore, RNF113A promotes chemoresistance to Cisplatin in lung cancer cells, at least by stabilizing MCL-1 levels." (PMID 32152280, 2020). "As MCL-1 promotes resistance to Cisplatin and because MCL-1 expression relies on RNF113A, we next explored whether RNF113A also contributes to resistance to Cisplatin in lung cancer cells." (PMID 32152280, 2020). "Our data has some clinical relevance as RNF113A and MCL-1 protein levels positively correlated in clinical cases of lung cancer." (PMID 32152280, 2020). "We also analyzed TCGA data and observed that both RNF113A and NUPR1 expression were indeed positively correlated in lung cancer." (PMID 32152280, 2020). "We characterized all transcripts whose splicing relies on RNF113A and also established a link between RNF113A and MCL-1 stabilization, with important consequences for the treatment of lung cancer cells showing some acquired resistance to BCL-2 inhibitors." (PMID 32152280, 2020). "Therefore, RNF113A expression prevents senescence, at least by maintaining NUPR1 expression in lung cancer cells." (PMID 32152280, 2020).
esophageal squamous cell carcinoma (2 papers, 2021 to 2024). Esophageal squamous cell carcinoma (ESCC) is a type of esophageal carcinoma (EC) that can affect any part of the esophagus, but is usually located in the upper or middle third. "A recent study identified the upregulation of RNF113A in esophageal squamous cell carcinoma compared with adjacent normal tissues and its roles in oncogenic properties." (PMID 38741949, 2024). "RNF113A was revealed to promote the proliferation, migration, and invasion in esophageal squamous cell carcinoma." (PMID 34195188, 2021).
acute myeloid leukemia (1 paper, 2025). Acute myeloid leukemia (AML) is a group of neoplasms arising from precursor cells committed to the myeloid cell-line differentiation. "The E3 ubiquitin ligase RNF113A mediates the ubiquitin/proteasome-dependent degradation of METTL3 through the K48-linked multi-ubiquitin chain, reducing the level of m6A modification to promote the inhibition of acute myeloid leukemia." (PMID 40495163, 2025).
leukemia (1 paper, 2023). A malignant (clonal) hematologic disorder, involving hematopoietic stem cells and characterized by the presence of primitive or atypical myeloid or lymphoid cells in the bone marrow and the blood. "For the functional study, we found that overexpression of RNF113A significantly inhibited AML cell proliferation, enhanced drug sensitivity, and effectively alleviated the leukemia-promoting effects caused by METTL3 overexpression in vitro." (PMID 37280654, 2023). "To assess RNF113A function in leukemia, we first knocked down RNF113A in myeloid leukemia cells using two siRNAs." (PMID 37280654, 2023). "RNF113A knockdown significantly promoted cellular growth and inhibited apoptosis of leukemia cells." (PMID 37280654, 2023). "Thus, we over-expressed RNF113A in Circ_0001187-knockdown leukemia cells and found that RNF113A restoration partially rescued the drug sensitivity defects caused by Circ_0001187 deficiency." (PMID 37280654, 2023).
lung adenocarcinoma (1 paper, 2022). A carcinoma that arises from the lung and is characterized by the presence of malignant glandular epithelial cells. "Intriguingly, RNF113A has been recently linked to cisplatin resistance in lung adenocarcinoma." (PMID 35819319, 2022). "Regardless of the mechanisms involved, RNF113A involvement in both cisplatin in lung adenocarcinoma and alkylation-based therapy resistance in SCLC is particularly attractive, as both agents are frequently used together in certain cancer combination treatments." (PMID 35819319, 2022).
trichothiodystrophy (1 paper, 2015). Trichothiodystrophy or TTD is a heterogeneous group disorders characterized by short, brittle hair with low-sulphur content (due to an abnormal synthesis of the sulfur containing keratins). "A mutation in another retrogene, RNF113A (ring finger protein 113A [MIM: 300951]), results in trichothiodystrophy." (PMID 26474060, 2015).
tumor (5 papers, 2020 to 2025). "RNF113A deficiency also triggered tumor regression in vivo upon treatment with Cisplatin when resistant A549 cells were transplanted into immunodeficient mice." (PMID 32152280, 2020). "Collectively, our findings highlight the potential clinical implications of Circ _0001187 as a key tumor suppressor in AML via the miR-499a-5p/RNF113A/METTL3 pathway." (PMID 37280654, 2023). "RNF113A expression was higher in our clinical cases of pulmonary adenocarcinomas than in tumor-free lung parenchymas, independently of the K-RAS or EGFR mutational status." (PMID 32152280, 2020). "RNF113A (ring finger protein 113A) was up-regulated in ESCC compared with the normal counterpart and it associated with poorly differentiated and late-stage tumours." (PMID 32429269, 2020). "Thus, both SMYD3 and RNF113A seem to be key proteins for tumor sensitivity and acquired resistance to various chemotherapeutic drugs." (PMID 35819319, 2022). "Circ_0001187 regulates AML progression through the miR-499a-5p/RNF113A/METTL3 axis and acts as a key tumor suppressor in AML." (PMID 41229443, 2025). "Upon UBE2C silencing there was a decrease in cell proliferation of EAC and ESCC cell lines, whereas RNF113A knockdown resulted in reduced proliferation and increased apoptosis, as well as inhibition of the migratory and invasive capacities of ESCC cell lines and decreased tumour growth in nude mice." (PMID 32429269, 2020). "However, how RNF113A is activated and regulated remains unclear, and we sought to determine whether the regulation of RNF113A activity by SMYD3 methylation may be a potential mechanism of tumor resistance to alkylation damage." (PMID 35819319, 2022).
cancer (3 papers, 2020 to 2024). A tumor composed of atypical neoplastic, often pleomorphic cells that invade other tissues. "We believe that our RNA sequencing analysis of RNF113A KO cells and the identification of the roles of RNF113A in ROS protective activities provide valuable insights into the potential role of RNF113A in human diseases, including X-linked TTD and cancer." (PMID 38741949, 2024). "Further research should determine the impacts of DNA repair activities and cellular protective roles of RNF113A in cancer development and progression." (PMID 38741949, 2024). "Because RNF113A acts upstream of the alkylation damage repair pathway by recruiting the ASCC complex, we reasoned that an upregulated response to alkylation damage may promote cancer cell tolerance to alkylating agents and explained the impact of SMYD3 in our SCLC and xenograft models." (PMID 35819319, 2022).
adenocarcinoma (1 paper, 2020). A common cancer characterized by the presence of malignant glandular cells. "RNF113A expression increased at both mRNA and protein levels in Cisplatin-treated A549 and BZR-T33 adenocarcinoma-derived cells." (PMID 32152280, 2020).
lung (1 paper, 2020). "A majority of lung malignancies showed a mostly nuclear staining of RNF113A." (PMID 32152280, 2020).
RNF113A also shares sentences with these, for which no sentence is quoted: Colon Cancer (1 paper); myeloid leukemia (1).